KISS1 (KiSS-1 metastasis suppressor)
Diseases named in the same sentence as KISS1 in open-access papers (continued):
Sharing a sentence is not in itself a finding about the gene and the disease.
colorectal cancer (14 papers, 2014 to 2026). A primary or metastatic malignant neoplasm that affects the colon or rectum. "KiSS1 is also epigenetically modified in colorectal cancer, and KiSS1 methylation is associated with tumor grade, predicted recurrence and overall survival." (PMID 25272010, 2014). "On the basis of the data from these experiments, Kiss-1 may play a metastasis suppressor role in human colorectal cancer and be linked to the disease progression of patients, by way of aberrant expression and molecular and cellular mechanism (s) that are yet to be identified." (PMID 25260785, 2014). "Finally, a recent report has shown that the reduction/loss of Kiss-1 in colorectal cancer may be the result of hypermethylation of Kiss-1, and this provides a plausible explanation for the reduction of Kiss-1 observed in the current study." (PMID 25260785, 2014). "Overexpression of KiSS-1 reduces the invasiveness of colorectal cancer cells by blocking the PI3K/AKT/NF-κB pathway and inhibiting the expression of MMP-9 protein." (PMID 31783709, 2019). "As an example shown here, L. lactis NZ9000 was demonstrated to be a cell factory for the secretion of biologically active KiSS1 protein, exerting inhibition effects on human colorectal cancer HT-29 cells." (PMID 27287327, 2016). "In this study, we examined the expression of Kiss-1 and Kiss-1R in human colorectal cancer and analyzed the potential clinical and prognostic implications." (PMID 25260785, 2014). "In conclusion, the present study has presented evidence that Kiss-1 is a putative metastasis suppressor molecule in human colorectal cancer." (PMID 25260785, 2014). "The mRNA and protein expression of Kiss-1 and Kiss-1R, and their correlation to the clinical outcome in human colorectal cancer were investigated using real-time PCR and IHC respectively." (PMID 25260785, 2014). "The stabilized transfected cells were then used to deduce the influence of Kiss-1 and Kiss-1R on the function of colorectal cancer cells by in vitro assays and ECIS assay." (PMID 25260785, 2014). "Additionally, research findings indicate that when KISS1 is overexpressed, it can lessen the invasion of colorectal cancer cells by impeding the PI3K/AKT signaling pathway." (PMID 41399389, 2026). "Interestingly, in cancers such as pancreatic, ovarian, and colorectal cancer, a new facet in the relationship between KISS1/KISS1R and these cancers was uncovered." (PMID 30123188, 2018). "Knocking down Kiss-1 resulted in increased invasion and migration of colorectal cancer cells." (PMID 25260785, 2014). "Therefore, the aim of this study was to investigate the role and signal transduction of Kiss-1 and Kiss-1R in colorectal cancer." (PMID 25260785, 2014). "Kiss-1 and Kiss-1R have been suggested as a novel pair of metastasis suppressors for several human solid tumours, however, their role in colorectal cancer remains largely unknown." (PMID 25260785, 2014). "The present study has presented evidence that Kiss-1 may be a putative metastasis suppressor molecule in human colorectal cancer." (PMID 25260785, 2014). "LoVo human colorectal carcinoma cells are deficient in furin activity; therefore, they were used as a negative control for KISS1 processing by furin." (PMID 24454770, 2014). "KiSS1 has been studied in various types of cancer and has been suggested to play multiple roles in cancer development and in suppression of metastasis, such as thyroid cancer, oesophageal carcinoma, urinary bladder cancer, gastric carcinoma, epithelial ovarian cancer, and colorectal cancer." (PMID 27287327, 2016). "However, few studies have specifically shown a role for Kiss-1 in colorectal cancer as yet." (PMID 25260785, 2014). "More recently, TCF21 was found to induce KISS-1 and reduce MMPs expression through the PI3K/Akt pathway in colorectal cancer." (PMID 35201460, 2021).
colorectal cancer (continued). "In human colorectal cancer tissues, the mRNA expression level of Kiss-1 had a negative correlation with Dukes staging, TNM staging, tumour size and lymph node involvement." (PMID 25260785, 2014). "One hypothesis to explain this may be that the inhibitory effect of Kiss-1 on colorectal cancer cells may not solely combine with Kiss-1R, but with other unknown receptors." (PMID 25260785, 2014).
bladder cancer (13 papers, 2003 to 2026). "Similar data were detected in an analysis of urinary bladder cancer samples: loss of KiSS-1 expression was found in all invasive cancers and the surrounding normal uroepithelium showed higher levels of KiSS-1 expression." (PMID 29662466, 2018). "Sanchez-Carbayo and co-workers found lower levels of KiSS-1 in bladder cancer tissues as compared to normal counterpart; also, they documented that the loss of KiSS-1 is associated with bladder cancer progression and clinical outcome." (PMID 29760678, 2018). "KiSS-1 has also been shown to influence cell adhesion by forming focal adhesions through phosphorylation of focal adhesion kinase and paxillin, and an association between loss of KiSS-1 expression and E-cadherin expression was reported in bladder cancer." (PMID 19154616, 2009). "In bladder cancer, loss of KiSS-1 expression is related to tumor progression." (PMID 19154616, 2009). "miR-3648 is overexpressed and promotes invasion and metastasis of human bladder cancer by directing transcription factor 21 (TCF21)/kisspeptin 1 (KISS1) axis." (PMID 35037826, 2022). "At the molecular level, the epigenetic silencing of KISS1 in bladder cancer is due to the upregulation of Ubiquitin-like with PHD and RING finger domains 1 (UHRF1)." (PMID 31336647, 2019). "Another type of cancer in which the expression of KiSS-1 is correlated with stage and tumor grade is bladder cancer." (PMID 29760678, 2018). "KiSS1 encodes the protein kisspeptin, a G-protein coupled receptor ligand for GPR54 and a metastasis suppressor in malignant melanoma and bladder cancer." (PMID 29674723, 2018). "The occurrence of an epigenetic regulation of KiSS-1 expression which favors bladder cancer invasion was confirmed by Zhang and co-workers." (PMID 29760678, 2018). "Multivariate analysis revealed that KISS1 expression was an independent predictor of bladder cancer metastasis and overall patient survival." (PMID 30123188, 2018). "In bladder cancer, in situ hybridization studies revealed that KISS1 expression was significantly decreased or lost in invasive bladder tumors (n = 173) compared with their respective normal urothelium (n = 25)." (PMID 30123188, 2018). "UHRF1 levels are relatively higher with concurrent low levels of KiSS1 in invasive bladder cancer cell lines." (PMID 25272010, 2014). "Our results revealed that UHRF1 expression is upregulated in primary tumors that subsequently metastasized, and overexpression of UHRF1 promotes bladder cancer cell invasion by epigenetic silencing of KiSS1." (PMID 25272010, 2014). "Previous studies showed that KiSS1 is frequently hypermethylated in bladder cancer and is correlated with cancer progression." (PMID 25272010, 2014). "UHRF1 decreases KiSS1 expression by increasing the methylation of CpG nucleotides of KiSS, and downregulation of KiSS1 promotes bladder cancer cell invasion." (PMID 25272010, 2014). "Our data showed that upregulated UHRF1 contributes to bladder cancer cell invasion by epigenetic silencing of KiSS1." (PMID 25272010, 2014). "We then assayed the expression level of UHRF1 and KiSS1 in both invasive bladder cancer cell lines and noninvasive bladder cancer cell lines." (PMID 25272010, 2014). "KiSS1 is identified as suppressing metastases in various cancers, such as bladder cancer, breast cancer cells and melanoma." (PMID 25272010, 2014). "The combination of separate expression profiling studies of bladder tumours and bladder cancer cell lines has allowed the identification of the tumour-suppressor role of KiSS-1 in bladder cancer progression." (PMID 14676790, 2003). "Lower transcript levels of KiSS-1 were observed in bladder carcinomas, as compared to superficial tumours, and these ratios provided prognostic information." (PMID 14676790, 2003). "Furthermore, in bladder cancer cells analyzed by methylation-specific PCR and bisulfite sequencing, KISS1 promoter hypermethylation was frequently reported and related to a low gene expression." (PMID 31336647, 2019).
bladder cancer (continued). "Furthermore, it was demonstrated that the upregulated UHRF1 promotes bladder cancer cell invasion by epigenetic silencing of KiSS1 metastasis suppressor gene coding for kisspeptin." (PMID 28128913, 2017). "Despite these intriguing findings, little is known about whether UHRF1 increases bladder cancer cell invasion by epigenetic silencing of KiSS1." (PMID 25272010, 2014). "In the study, we tested whether UHRF1/KiSS1 represents a novel pathway regulating bladder cancer cell invasion." (PMID 25272010, 2014). "Recent studies showed that KiSS1 is epigenetically silenced by hypermethylation in bladder cancer." (PMID 25272010, 2014). "Here we investigated whether UHRF1 regulates bladder cancer cell invasion by epigenetic silencing of KiSS1." (PMID 25272010, 2014). "We first assayed whether KiSS1 inhibition increases bladder cancer cell invasion." (PMID 25272010, 2014). "We therefore investigated whether UHRF1 promotes bladder cancer cell invasion by inhibiting KiSS1." (PMID 25272010, 2014).
ovarian carcinoma (12 papers, 2007 to 2025). A malignant neoplasm originating from the surface ovarian epithelium. "KISS1 expression levels have also been linked to survival in ovarian cancer patients as reported in several studies." (PMID 30123188, 2018). "Altogether, these results are indicative of the tumor suppressing nature of Kiss1 and its receptor, Kiss1R, in ovarian cancer." (PMID 28439256, 2017). "Despite the similarity of Kiss1R expressions levels between malignant and benign ovarian tumors, the expression of Kiss1 was found to be significantly higher in malignant ovarian tumors." (PMID 28439256, 2017). "Based on the various ovarian cancer studies, the independent findings propose that KISS1/KISS1R protein levels could be used as prognostic biomarkers of disease progression in ovarian cancer." (PMID 30123188, 2018). "Similarly, in ovarian cancer patients, lower KiSS-1 gene expression was related to more resistant ovarian cancers, cell invasion, the presence of macroscopic residual tumor following surgical resection, and the patient’s worse prognosis." (PMID 29662466, 2018). "However, recent evidence suggests that kisspeptin (Kiss1) and Kiss1R are involved in ovarian cancer progression." (PMID 28439256, 2017). "In ovarian carcinoma the increased expression of KISS1 has been shown to inhibit cell migration." (PMID 24528603, 2014).
diabetes (10 papers, 2014 to 2025). "A rat model of diabetes (streptozocin treated) has reduced levels of hypothalamic Kiss1 mRNA with subsequently low levels of circulating gonadotrophins and sex steroids, which are corrected by kisspeptin." (PMID 24615662, 2014). "Additionally, Kiss1 mRNA expression in the whole hypothalamus was reduced 4 weeks after STZ injection in female rats with long-term diabetes." (PMID 35084363, 2022). "However, Kiss1 mRNA in the hypothalamus decreased in male rats with long-term diabetes (4 weeks after STZ injection)." (PMID 35084363, 2022). "However, exogenous injections of insulin did not reverse the decreased Kiss1 gene expression, which was induced by fasting- and diabetes-associated metabolic perturbations." (PMID 29643834, 2018). "In this article, we provide an overview of the KISS1/KISS1R system and its involvement in diseases such as reproductive disorders, cancer, diabetes, and cardiovascular disease." (PMID 40430029, 2025). "However, the high BMI subjects in the Kolodziejskii study specifically excluded those with diabetes and they would not exhibit hyperglucagonemia and the resulting increased hepatic Kiss1 expression." (PMID 29740399, 2018). "Therefore, the suppression of Kiss1, Tac3, and Pdyn expression in severely diabetic rats 8 weeks after STZ injection observed in the present study might be rapidly induced by STZ administration and might not be a gradual induction in proportion to the severity of diabetes." (PMID 35084363, 2022).
gastric cancer (9 papers, 2009 to 2021). A primary or metastatic malignant neoplasm involving the stomach. "In gastric cancer, lower expression of KiSS-1 mRNA is associated with venous invasion, distant metastasis, and tumor recurrence." (PMID 19154616, 2009). "KiSS1 has been demonstrated as a suppressor of metastasis in the majority of cancers, including gastric cancer, oesophageal carcinoma, pancreatic, ovarian, bladder and prostate cancer." (PMID 29721201, 2018). "Immunohistochemical analysis of tissue microarrays from 71 patients with gastric cancer revealed a statistically significant reduction of KiSS-1 in lymph node and liver metastases compared with primary tumors." (PMID 29760678, 2018). "Indeed, the low expression of KiSS-1 in tumor tissues was documented to correlate with the propensity of gastric cancers to invade, metastasize, and relapse as well as to worse overall and disease-free survival." (PMID 29760678, 2018). "Furthermore, KiSS-1 is an independent prognostic marker for gastric cancer according to multivariate analysis." (PMID 19154616, 2009). "Notably, KISS1, TIMP2, MMP11, IGFBP1, and EGFR have been reported to be involved in the metastasis of gastric cancer." (PMID 32117443, 2020). "A study on 40 gastric cancers divided into two groups according to their high or low KiSS-1 mRNA expression levels and compared with their adjacent normal gastric mucosa, demonstrated that KiSS-1 may represent an independent prognostic factor for gastric cancer patients." (PMID 29760678, 2018).
Anxiety (8 papers, 2012 to 2024). Intense feelings of nervousness, tension, or panic often arise in response to interpersonal stresses. "However, in zebrafish, habenula Kiss1 neurons have been associated with the modulation of serotonin neurons, fear-like responses and aversive memory and learning (see section “Fear- and Anxiety- Like Behaviors” for more details)." (PMID 35221943, 2021). "Hence, habenula Kiss1 could act as a sensor for stressful or socially aversive conditions and modulate the subsequent stress-coping behavior such as mobility (avoidance), anxiety and aversion-associated learning." (PMID 35221943, 2021). "Since both pheromones and anxiety can affect LH secretion and the reproductive axis, this suggests that the communication between the MeA and Kiss1 neurons in the ARC is physiologically relevant." (PMID 30917148, 2019). "Questions about KISS1 and its relation to mood or social behavior, resulting in anxiety and depression, are only recently being addressed, even though stress-induced increases in adrenal glucocorticoids are known to suppress the HPG axis, and reproductive dysfunctions lead to mood changes in humans." (PMID 36004833, 2022).
endometriosis (8 papers, 2020 to 2025). The growth of functional endometrial tissue in anatomic sites outside the uterine body. "This integrated ultrastructural and molecular analysis provides novel insights into the pathophysiological role of nuclear KiSS-1 and its potential as a diagnostic and therapeutic target in endometriosis." (PMID 41567980, 2025). "Given the distinct nuclear and cytoplasmic localization patterns of KiSS-1 in eutopic and ectopic endometrium, future studies could explore its potential as a diagnostic or prognostic biomarker for endometriosis progression." (PMID 41567980, 2025). "Results indicated lower levels of KISS1 and KISS1R in the eutopic endometrium of patients with endometriosis compared to controls, suggesting that a deficiency in KISS1 and KISS1R may promote tissue invasion and contribute to endometriosis pathogenesis." (PMID 39768606, 2024). "KiSS-1 is also present in the endometrium, where it may influence uterine growth, and its disruption is linked to gynecologic disorders including endometriosis." (PMID 41567980, 2025). "This integrated mechanistic view provides a strong rationale for exploring KiSS-1 analogues or agonists to therapeutically modulate lesion progression or invasive behavior in endometriosis and other pathologies sharing metastatic-like features." (PMID 41567980, 2025). "In women with endometriosis, the expression of the KISS1 gene in the endometrium is lower compared to that in ectopically implanted tissue." (PMID 40429279, 2025). "Earlier reports generally described predominantly cytoplasmic staining and and lower KiSS-1 levels in eutopic tissue from endometriosis patients." (PMID 41567980, 2025). "Tissue samples from 35 women with endometriosis and 14 control subjects were tested with KISS1 and KISS1R antibodies." (PMID 39768606, 2024). "It has been found that in the cell culture of endometriosis patients, the KISS1 level was lower, and the migration activity of this line was statistically increased in comparison with the control group." (PMID 38255200, 2024). "Our findings are consistent with the hypothesis that a lower expression of KISS1/KISS1R contributes to the pathogenesis of endometriosis by increasing invasion of tissues." (PMID 38255200, 2024). "The maximum values of KISS1/KISS1R were recorded at stage IV of endometriosis." (PMID 38255200, 2024). "We presume that the dysregulation of KISS1 and MMPs might contribute to endometriosis pathogenesis." (PMID 38255200, 2024). "Collectively, these findings contribute new insights into the cellular pathology of endometriosis and reinforce the relevance of the PI3K/AKT signaling and KiSS-1 expression within its molecular landscape." (PMID 41567980, 2025). "In both eutopic and ectopic endometrium from patients with endometriosis, PI3K and AKT expression levels were significantly increased, whereas KiSS-1 expression was reduced and showed nuclear localization in a subset of cells." (PMID 41567980, 2025). "Therefore, we may presume that KISS1, KISS1R, MMP-2, and MMP-9 can be used for the diagnostic, assessment of the progression of endometriosis and the effectiveness of treatment of this disease in women from 23 to 38 years old without endocrine system pathology and oncology diseases." (PMID 38255200, 2024). "Since MMP-2 and MMP-9 can break down and inactivate KISS1, an increase of MMP activity in endometriosis can work through feedback to decrease KISS1 levels, additionally eliminating possible inhibiting effects of KISS1 on migration and invasion." (PMID 38255200, 2024). "The relative level of KISS1 mRNA expression showed a statistically significant decrease in stages II and III of extragenital endometriosis; they were 3.5 and 1.9 times lower, respectively, compared with the control." (PMID 38255200, 2024). "The aim of our study was to study KISS1/KISS1R, MMP-2, and MMP-9 gene expression and protein synthesis in endometriosis and compare them with the normal endometrium." (PMID 38255200, 2024).